ING1 (inhibitor of growth family member 1)
Diseases named in the same sentence as ING1 in open-access papers (continued):
Sharing a sentence is not in itself a finding about the gene and the disease.
ING1 also shares sentences with these, for which no sentence is quoted: colorectal cancer (4 papers); breast tumors (3); hepatocellular carcinoma (2); oral squamous cell carcinoma (2); acute lymphoblastic leukemia (1); acute myeloid leukemia (1); Alzheimer disease (1); astrocytoma (1); breast adenocarcinoma (1); cervical cancer (1); colon tumor (1); COVID-19 (1); hereditary angioedema (1); histiocytic sarcoma (1); laminopathy (1); liver cancer (1); lymph node metastasis (1); malignant glioma (1); meningioma (1); oligodendroglial tumor (1); ovarian carcinoma (1); squamous cell carcinoma (1).